EGFR (epidermal growth factor receptor)
Diseases named in the same sentence as EGFR in open-access papers (continued):
Sharing a sentence is not in itself a finding about the gene and the disease.
non-small cell lung carcinoma (continued). "Epidermal growth factor receptor (EGFR) mutations activated in non-small cell lung cancer (NSCLC) are effective targets for EGFR tyrosine kinase inhibitors (TKIs)." (PMID 35402377, 2022). "TKIs that target sensitizing mutations in the EGFR gene are a key pillar of the treatment of non-small-cell lung cancer." (PMID 35663041, 2022). "In general, non-small cell lung cancer patients with epidermal growth factor receptor (EGFR) mutations respond to tyrosine kinase inhibitors (TKIs)." (PMID 36158654, 2022). "Gefitinib has shown promising efficacy in the treatment of patients with locally advanced or metastatic EGFR-mutated non-small cell lung cancer (NSCLC)." (PMID 35978819, 2022). "We report that exosomes from serum of patients with Epidermal Growth Factor Receptor (EGFR) -mutated non-small cell lung cancer (NSCLC) induce invasion by promoting hybrid EMT." (PMID 35954442, 2022). "Consistent with this idea, previous studies have indicated that increased TGFBR2 expression is associated with resistance to ALK and EGFR inhibitors in non-small cell lung carcinoma." (PMID 33837205, 2021). "In this chronic exposure, the participation of hypoxia in tumorigenesis is significant; for example, in patients with non-small-cell lung cancer, recurrent mutations of the epidermal growth factor receptor (EGFR) have been associated with hypoxia." (PMID 34361103, 2021). "EGFR mutation has been detected in more than half of non-small cell lung cancer (NSCLC) patients in Asia." (PMID 34505336, 2021). "Circulating cell-free DNA (cfDNA) level has been demonstrated to be associated with efficacy in first generation EGFR TKIs in non-small cell lung cancer (NSCLC)." (PMID 33842353, 2021). "Advanced non-small-cell lung cancer (aNSCLC) harboring activating epidermal growth factor receptor (EGFR) mutation benefits from oral tyrosine-kinase inhibitors (TKIs) such as gefitinib, erlotinib, afatinib and osimertinib." (PMID 34069851, 2021). "Analysis of vesicles-associated nucleic acids for BRAF, KRAS, and EGFR mutations has shown higher sensitivity compared to plasma ctDNA in non-small cell lung cancer (NSCLC) patients." (PMID 34178690, 2021). "Leptomeningeal metastasis (LM) is a commonly observed complication in patients with epidermal growth factor receptor (EGFR)-mutated non-small cell lung cancer (NSCLC)." (PMID 35127465, 2021). "This attitude is supported by studies showing favorable outcomes of tyrosine kinase inhibitors in first- or second-line treatment in older or frail patients with EGFR mutation-positive non-small cell lung cancer." (PMID 35008257, 2021). "It is a small subset of the possible resistance mechanisms, even in epidermal growth factor receptor (EGFR)-mutated non-small cell lung cancer treated with EGFR-tyrosine kinase inhibitors." (PMID 34094904, 2021). "This test is used to guide the use of epidermal growth factor receptor (EGFR)-tyrosine kinase inhibitors on the basis of specific EGFR-sensitizing mutations in patients with non-small cell lung cancer (NSCLC)." (PMID 33593396, 2021). "In EGFR mutated non-small cell lung cancer acquired tyrosine kinase inhibitor resistance, the resistance relies on EGFR palmitoylation and FASN." (PMID 34803494, 2021). "For example, identifying the EGFR T790M mutation in plasma samples is already known to be an effective method for determining EGFR status in patients with non-small cell lung cancer (NSCLC)." (PMID 34458320, 2021). "Rociletinib is a third generation EGFR inhibitor that in a phase I/II trial has demonstrated efficacy in patients with EGFR-mutant non-small cell lung cancer with the T790M resistance mutation who progressed on standard anti-EFGR treatment." (PMID 34830886, 2021). "The study aimed to compare the efficacy of osimertinib plus cranial radiotherapy (RT) with osimertinib alone in advanced non-small-cell lung cancer (NSCLC) patients harboring epidermal growth factor receptor (EGFR) mutations and brain metastases (BMs)." (PMID 34865626, 2021).
non-small cell lung carcinoma (continued). "As we all know, EGFR-mutated non-small-cell lung cancer was highly sensitive to a variety of EGFR inhibitors, and our results also predict that EGFR was the responsive gene of Vandetanib, Lapatinib, Gefitinib, Canertinib, and Afatinib." (PMID 34356665, 2021). "In non-small cell lung cancers (NSCLC) harboring EGFR mutations, the understanding of molecular and genetic intratumor heterogeneity has emerged as a pivotal task in the individualization process of cancer treatment." (PMID 33804833, 2021). "Epidermal growth factor receptor (EGFR) mutations are observed in a big proportion of patients with non-small cell lung cancer (NSCLC) from Asian populations." (PMID 34181354, 2021). "To test this, we selected 22 non-small cell lung cancer (NSCLC) patients with known EGFR E19del/L858R mutations in tumor tissues." (PMID 34178690, 2021). "Osimertinib is a standard of care therapy for previously untreated epidermal growth factor receptor mutation-positive non-small cell lung cancer." (PMID 34848786, 2021). "Exosome-derived EGFR has been identified as a diagnostic marker for non-small cell lung cancer (NSCLC) based on its high expression in plasma exosomes of patients with NSCLC." (PMID 34769444, 2021). "In colorectal and non-small-cell lung cancers, resistance to EGFR inhibitors develops due to secondary mutations in EGFR or mutations in downstream effectors such as KRAS (Kirsten Rat Sarcoma Viral Oncogene Homolog) or BRAF." (PMID 34461089, 2021). "Tid1, acting as a tumor suppressor, interacts with EGFR/HSP70/HSP90 by DnaJ domain and causes EGFR degradation in non-small cell lung cancer (NSCLC) and in head and neck squamous cell carcinoma (HNSCC)." (PMID 33406664, 2021). "Mutations within the kinase domain of the epidermal growth factor receptor (EGFR) are common oncogenic driver events in non-small cell lung cancer." (PMID 34319231, 2021). "The burden of epidermal growth factor receptor (EGFR) exon 20 insertion mutation (Exon 20ins) in non-small cell lung cancer is not well understood." (PMID 33684140, 2021). "Approximately 3–5% of patients with epidermal growth factor receptor (EGFR) mutation-positive non-small cell lung cancer (NSCLC) harbor exon 18 mutations." (PMID 34540680, 2021). "Limited therapeutic options are left for non-small cell lung cancer (NSCLC) harbouring sensitizing EGFR mutations after failure of EGFR-tyrosine kinase inhibitor (TKI) therapy and chemotherapy, finding effective options for them is an unmet clinic need." (PMID 34628779, 2021). "This framework is preliminarily tested in a study predicting the epidermal growth factor receptor (EGFR) mutation status in non-small cell lung cancer (NSCLC) patients." (PMID 33681463, 2021). "The implementation of diagnostics using ctDNA has been leveraged as a companion diagnostic test, e.g., for detecting EGFR inhibitor sensitive mutations for the use of erlotinib in non-small cell lung cancer." (PMID 34298813, 2021). "In non-small cell lung cancer, radiomics on computed tomography (CT) can predict tumor stage and epidermal growth factor receptor (EGFR) mutation status." (PMID 33915880, 2021). "Epidermal growth factor receptor (EGFR) tyrosine kinase inhibitors (TKIs) are approved treatments for non-small-cell lung cancer (NSCLC) patients harboring activating EGFR mutations." (PMID 34572484, 2021). "The Cobas®EGFR mutation detection kit, which detects EGFR mutations of non-small-cell lung cancer, and the OncoBEAM RAS CRC Kit, which detects RAS mutations of colorectal cancer, have been approved in Japan as companion diagnostics." (PMID 33249514, 2021). "EGFR, harboring activating mutations, drives unlimited cell proliferation in non-small cell lung cancer (NSCLC), and treatment of tumors with tyrosine kinase inhibitors (TKIs) results in growth arrest and cell death." (PMID 33922104, 2021).
non-small cell lung carcinoma (continued). "The role of activating mutations in the epidermal growth factor receptor (EGFR) gene in non-small cell lung cancer (NSCLC) was reported in 2004." (PMID 34831415, 2021). "To date, there is no targeted therapy approved and demonstrated to be effective for non-small cell lung cancer patients with EGFR sensitizing mutations, and ERBB2 amplification." (PMID 33663050, 2021). "A CRISPR functional genomic screen revealed that FGFR signaling contributed to the resistance of the EGFR gatekeeper mutation (EGFR-T790M) to EGFR inhibition in EGFR-driven non-small cell lung cancer." (PMID 34638374, 2021). "Background and Objectives: Epidermal growth factor receptor–tyrosine kinase inhibitors (EGFR-TKIs) are effective first-line chemotherapeutic agents for patients with advanced non-small-cell lung cancer (NSCLC) harboring drug-sensitive EGFR mutations." (PMID 34577852, 2021). "In this review, we discuss the molecular epidemiology of the main druggable genetic alterations in non-small cell lung cancer, namely EGFR, KRAS, BRAF, MET, and HER2 mutations or amplification, as well as ALK and ROS1 fusions." (PMID 33435440, 2021). "Tyrosine kinase inhibitors (TKIs) are the first-line therapy for non-small-cell lung cancers (NSCLC) that harbour sensitising mutations within the epidermal growth factor receptor (EGFR)." (PMID 34572879, 2021). "Rarely, dominantly inherited non-small-cell lung cancer (NSCLC) has been reported due to somatic mutations in EGFR/ErbB1 and ERBB2." (PMID 34274969, 2021). "The guidelines recommended gefitinib as a first-line targeted treatment for stage IV non-small-cell lung cancer (NSCLC) patients with EGFR mutations." (PMID 34160440, 2021). "For example, gefitinib, erlotinib, and afatinib are potent targeted agents that are used for the treatment of advanced non-small cell lung cancers in which the gene coding for the epidermal growth factor receptor (EGFR) has been mutated." (PMID 34621291, 2021). "In summary, herein, we revealed that quercetin is an effective inhibitor for the treatment of non-small-cell lung cancer harboring the EGFR C797S mutation." (PMID 34572484, 2021). "Our study demonstrates data on the frequency of KRAS and EGFR mutations in a large cohort of patients diagnosed with non-small cell lung cancer that underwent surgical resection treatment over a defined period in Halifax, Canada." (PMID 33956842, 2021). "Epidermal growth factor receptor-tyrosine kinase inhibitors (EGFR-TKIs) are widely used as molecularly targeted drugs for non-small cell lung cancer (NSCLC) harboring EGFR-activating mutations." (PMID 34608255, 2021). "Few biomarkers predicted the efficacy of ICIs as accurate as EGFR mutations in predicting the efficacy of TKIs in non-small cell lung cancer." (PMID 34234847, 2021). "Epidemiology shows that approximately 30–40% of non-small cell lung cancer (NSCLC) patients have epidermal growth factor receptor (EGFR) mutations." (PMID 34054543, 2021). "Osimertinib is the first adjuvant targeted therapy to show a significant and clinically relevant advantage in disease-free survival in EGFR-mutated non-small cell lung cancer (NSCLC) after complete tumor resection." (PMID 33456617, 2021). "EGFR mutations represent the most common currently targetable oncogenic driver in non-small cell lung cancer." (PMID 33869038, 2021). "EGFR tyrosine kinase inhibitors (TKIs) are the front-line treatment in EGFR mutation positive advanced non-small cell lung cancer (aNSCLC) patients." (PMID 34179028, 2021). "Several retrospective studies present evidence of oligoprogressive disease (OPD) in patients with non-small cell lung cancer (NSCLC) with driver mutations such as EGFR." (PMID 34830977, 2021). "In contrast, 10–20% of patients with non-small cell lung cancer (NSCLC) harbor uncommon or rare EGFR mutation." (PMID 34540680, 2021).
non-small cell lung carcinoma (continued). "We also determined that the non-expression of CD133 was associated with a low degree of histological differentiation, disease progression, distant metastasis, and worse overall survival in EGFR-mutated non-small cell lung cancer patients." (PMID 34771484, 2021). "These are applied to non-small cell lung cancer cell lines with EGFR and T790M mutations that are resistant to primary drugs." (PMID 34683198, 2021). "In vitro, fedratinib significantly enhanced the cytotoxicity of erlotinib in erlotinib-resistant non-small cell lung carcinoma (NSCLC) cells with epidermal growth factor receptor mutations, and inhibited tumor growth of erlotinib-resistant NSCLC cells in vivo." (PMID 32647323, 2021). "Recently, a crucial side effect has arisen as a lung-specific toxicity caused by an epidermal growth factor receptor (EGFR) tyrosine kinase inhibitors (TKIs) for the treatment of non-small cell lung cancer (NSCLC)." (PMID 33533965, 2021). "The SOD rs4880 variant is associated with the epidermal growth factor receptor (EGFR) Leu858Arg mutation in patients with non-small-cell lung cancer and primary brain tumors." (PMID 34298760, 2021). "The treatment sequence of immunotherapy (IO) and epidermal growth factor receptor (EGFR) tyrosine kinase inhibitors (TKIs) is of great importance for the survival of non-small cell lung cancer (NSCLC) patients with EGFR sensitive mutation." (PMID 34249697, 2021). "This frontier research was further evaluated by Song’s study on progression-free survival prediction in non-small cell lung cancer patients with EGFR mutations." (PMID 33574448, 2021). "The controlling of acquired resistance or optimization of the afatinib dosage in EGFR/T790M mutation-positive non-small-cell lung cancer (NSCLC) is still an important fundamental problem." (PMID 34122668, 2021). "For example, the mutational status of EGFR in Non-Small Cell Lung Cancer (NSCLC) is an FDA-approved marker of response to Erlotinib." (PMID 34680436, 2021). "For example, identifying EGFR-tyrosine kinase (PTK) mutations from ctDNA for diagnostic purposes in patients with non-small cell lung cancer (NSCLC)." (PMID 35096878, 2021). "Patients suffering from Non-Small Cell Lung Cancer (NSCLC) with EGFR mutations had strikingly poor responses to PD-1 based immunotherapies compared to those with wt EGFR." (PMID 35052732, 2021). "Central nervous system (CNS) metastases are one of the most lethal complications of epidermal growth factor receptor (EGFR) mutation-positive non-small-cell lung cancer (NSCLC)." (PMID 34359582, 2021). "This study aims to develop a CT-based radiomics approach for identifying the uncommon epidermal growth factor receptor (EGFR) mutation in patients with non-small cell lung cancer (NSCLC)." (PMID 34976788, 2021). "The presence of an EGFR activating mutation in tumors of non-small-cell lung cancer patients enables effective targeted therapy towards EGFR." (PMID 34298851, 2021). "The antitumor activity was significantly enhanced without weight loss or damage to kidney and spleen in nude mice bearing EGFR-expressing non-small cell lung carcinoma." (PMID 33981532, 2021). "Patients with advanced non-small-cell lung cancer (NSCLC) with activating mutations in the epidermal growth factor receptor (EGFR) gene are eligible for EGFR tyrosine kinase inhibitors (TKIs)." (PMID 34026599, 2021). "Patients with epidermal growth factor receptor (EGFR) mutation-positive non-small-cell lung cancer can have central nervous system (CNS) metastases during their disease course." (PMID 34359582, 2021). "EGFR mutation analysis in non-small-cell lung cancer (NSCLC) patients is currently standard-of-care." (PMID 34298851, 2021). "Epidermal growth factor receptor tyrosine kinase inhibitors (EGFR-TKIs) are the preferred treatment for intermediate to advanced stage non-small cell lung cancer (NSCLC) in patients with EGFR gene mutation." (PMID 34646330, 2021).
non-small cell lung carcinoma (continued). "Treatment paradigms for metastatic non-small cell lung cancer are increasingly based on biomarker-driven therapies, with the most common alteration being mutation in the epidermal growth factor receptor (EGFR)." (PMID 35201504, 2021). "This changed particularly when a small percentage of non small cell lung cancer (NSCLC) were identified with mutations in the EGFR gene that rendered those tumors sensitive to the EGFR tyrosine kinase inhibitors (TKI)." (PMID 34048189, 2021). "An association between EGFR activity and an immune cold phenotype has been previously reported in multiple cancers, including HNSCC, and clinical trials reported lower benefit from ICI therapy for non-small cell lung cancer with EGFR mutations." (PMID 33800421, 2021). "Activating mutations in the epidermal growth factor receptor (EGFR) gene in non-small-cell lung cancer (NSCLC) lead to an increase in growth factor signaling activity and susceptibility to tyrosine kinase inhibitors (TKIs)." (PMID 34315431, 2021). "Tyrosine kinase inhibitors (TKIs) therapy targets at epidermal growth factor receptor (EGFR) gene mutations in non-small-cell lung cancer (NSCLC)." (PMID 33647045, 2021). "Approximately 30% of non-small cell lung cancer (NSCLC) tumors harbor a mutation in the epidermal growth factor receptor (EGFR) gene, with geographical variation in rates reported to be highest in Asia (38%) and lowest in Europe (14%)." (PMID 33684140, 2021). "Epidermal growth factor receptor (EGFR) mutations are the most common driver genes in non-small cell lung cancer (NSCLC), especially in the Asian population." (PMID 33450879, 2021). "Patients with EGFR mutations in non-small cell lung cancer (NSCLC) have been greatly benefited from gefitinib, however, the therapeutic has failed due to the presence of acquired resistance." (PMID 34775471, 2021). "In this work, an ECL-RET biosensor comprising graphitic carbon nitride quantum dots was assessed for the amplification-free detection in the blood plasma of DNA molecules coding for the EGFR L858R mutation, which is associated with non-small-cell lung cancer." (PMID 34522862, 2021). "According to NCCN Non-small Cell Lung Cancer Clinical Practice Guidelines (Version 1.2021), TKIs are the first-line treatment for patients with EGFR-sensitive mutations." (PMID 34222178, 2021). "For example, kinase inhibitors against the epidermal growth factor receptor (EGFR), like gefitinib and erlotinib, are used for the treatment of non-small cell lung cancer (NSCLC) patients with activating mutations in the EGFR gene." (PMID 34917620, 2021). "Afatinib is approved globally for EGFR-TKI treatment-naïve patients with EGFR mutation-positive non-small cell lung cancer (NSCLC)." (PMID 34253172, 2021). "For example, several studies have shown the reduced efficacy of ICIs in Non-Small Cell Lung cancer patients harboring EGFR mutations and ALK rearrangements." (PMID 33853586, 2021). "Mutations of epidermal growth factor receptors play a pivotal role in different cancers, and several drugs are already approved for specific subsets of malignancies, i.e., EGFR-mutated non-small cell lung cancer and colorectal cancer." (PMID 34768421, 2021). "Gefitinib is a selective small-molecule epidermal growth factor receptor (EGFR) tyrosine kinase inhibitor (TKI) that is approved for the treatment of advanced non-small-cell lung cancer (NSCLC) with mutations of EGFR that are sensitive to gefitinib." (PMID 34354759, 2021). "Clinical evidence has shown that few non-small cell lung cancer (NSCLC) patients with epidermal growth factor receptor (EGFR) mutations can benefit from immunotherapy." (PMID 34136375, 2021). "Of these, EGFR-tyrosine kinase inhibitor (TKI) was recommended by treatment guidelines as first-line treatment for EGFR-mutated advanced non-small cell lung cancer." (PMID 34434112, 2021).